RNU6-847P (RNA, U6 small nuclear 847, pseudogene)
Gene: Small nuclear RNA gene on chromosome 10 (34,926,775 to 34,926,882, forward strand). Ensembl gene ENSG00000223047.
Homologues: Orthologues: macaque U6 (92% identical), chimpanzee U6 (89% identical), dog U6 (82% identical). Paralogues in human: RNU6-1091P (84% identical), RNU6-445P (81% identical), RNU6-589P (81% identical), RNU6-737P (81% identical), RNU6-1024P (81% identical), RNU6-1147P (81% identical), RNU6-1287P (81% identical), RNU6-15P (81% identical), RNU6-166P (81% identical), RNU6-169P (81% identical), RNU6-31P (81% identical), RNU6-41P (81% identical), and 1288 more.